NEAT1 (nuclear paraspeckle assembly transcript 1)
Diseases named in the same sentence as NEAT1 in open-access papers (continued):
Sharing a sentence is not in itself a finding about the gene and the disease.
infection (39 papers, 2011 to 2025). The state of being infected such as from the introduction of a foreign agent such as serum, vaccine, antigenic substance or organism. "Pathogenic infections represent other types of cellular stress, and NEAT1 expression was reported to be induced in HeLa cells by influenza virus or herpes simplex virus infection." (PMID 31889167, 2019). "In addition, the downregulation of lnc RNA such as NEAT1 has been implicated in defective B cell activation and mucosal antibody production during infection." (PMID 40969755, 2025). "NEAT1 was first linked to an infection with the human immunodeficiency virus (HIV-1) in 2013." (PMID 30717168, 2019). "The expressions of lncRNAs UCA1, GAS5, NORAD, BISPR, and NEAT1 were quantified using Illumina cDNA (RNA-seq) sequencing data and compared to dRNA-seq using fold change expression in infection (normalized reads in infected/normalized reads in uninfected)." (PMID 41267684, 2025). "Together, these experiments demonstrate that NEAT1 expression can be induced by infections with several viruses." (PMID 41208976, 2025). "In this study, we observed that robust expression of NEAT1 was induced by infections with IAV and several other viruses." (PMID 41208976, 2025). "Under our experimental condition, all NEAT1-/- mice died within 6 days post infection (dpi), whereas approximately 60% of WT mice still survived at this time point." (PMID 41208976, 2025). "A prominent example is the NEAT1, which exhibits upregulation in most infections and assumes crucial anti-viral functions, thereby potentially serving as a therapeutic target for antisense and small molecule RNA inhibitor approaches." (PMID 38542512, 2024). "NEAT1, a lncRNA, emerges as a biomarker for S. typhimurium infection, and is significantly upregulated during infection, serving as a differential marker from other Salmonella strains or heat-inactivated S. typhimurium." (PMID 38542512, 2024). "We found that the viral RNA alteration seemed to be modest at the early infection stage (12 hpi) after silencing NEAT1-2, while the difference would be augmented at the late stage (36 hpi)." (PMID 35495674, 2022). "NEAT1 knockdown by LV-sh-NEAT1 infection significantly alleviated the lung tissue injury induced by LPS." (PMID 32089649, 2020). "Recently, two independent groups provided data on NEAT1 upregulation after an infection with the herpes simplex virus (HSV)." (PMID 30717168, 2019). "The lncRNA NEAT1 can up-regulate anti-HIV factors during infection and promote human immunodeficiency virus 1(HIV-1) replication." (PMID 30971240, 2019). "Of note, the expression of Neat1 is stimulated by many stimuli that also activate inflammasome, including infection of various viruses and some intracellular damages (e.g., ROS) that stabilize hypoxia-inducible factors (HIFs) and the tumor suppressor p5338–40." (PMID 30940803, 2019). "NEAT1 expression is induced upon infection with several RNA and DNA viruses, leading to a rapid accumulation of paraspeckles in the nucleus of the infected cells." (PMID 30646609, 2019). "Similar to the data obtained from HUVECs, NEAT1 was indeed upregulated by HTNV at a multiplicity of infection (MOI) of 1 beginning at 24 hpi in HUVECs and A549, HEK293, and HeLa cells, and the increasing tendency occurred in a time-dependent manner." (PMID 28202761, 2017). "In addition, we investigated the effects of NEAT1 on infections with H9N2 strain of avian influenza virus (AIV) and other RNA viruses, such as MDRV and SeV." (PMID 41208976, 2025). "Additionally, infections with other RNA viruses, including SeV and MDRV, and DNA viruses such as PRV also caused a significant increase in NEAT1 expression." (PMID 41208976, 2025). "Given its established nuclear role, we investigated whether the subcellular localization of NEAT1 varies depending on the stage of infection." (PMID 40429887, 2025).
infection (continued). "Based on current research and the results of this study, we speculated that the human body can highly express lncRNA NEAT1 after infection with Mtb, which may be involved in the proinflammatory response through the polarization of macrophages M1." (PMID 35465262, 2022). "Moreover, the decreased levels of TNF-α, IL-6, IL-8 and IL-β in LPS+si-NEAT1 group were overturned following infection with anti-miR-370-3p." (PMID 32414769, 2020). "Prior evidence has indicated that lncRNA NEAT1 plays a role in the modulation of multiple genes and pathways, thereby inducing inflammation disorder and infection, as well as exaggerating inflammatory response and infection." (PMID 33042992, 2020). "Using siRNA and NEAT1 knockout mice, we found that increased NEAT1 expression during tuberculosis infection was related with an increase in infection duration and that decreased NEAT1 expression may induce macrophage clearance of Mycobacterium tuberculosis from cells." (PMID 35457250, 2022). "Thus, the changes in DANCR and NEAT1 may lead to the infection-related impact of those miRs and regulate the inflammation signature associated with them in epithelial cells, albeit in a sex-related manner." (PMID 33163005, 2020). "In addition, Mtb infection could increase the level of NEAT1 and further enhance continuous infection by promoting the release of inflammatory factors via multiple signaling pathways." (PMID 30534569, 2018). "Similar to a study on nuclear paraspeckle assembly transcript 1 in HSV-1 replication, it found that infection upregulates expression." (PMID 40144645, 2025). "The NEAT1-/- and WT mice were then intranasally inoculated with IAV PR8 virus, and the influence of NEAT1 knockout on IAV virulence and infection kinetics was examined." (PMID 41208976, 2025). "A time-course study also showed that NEAT1 was induced by IAV infection, and its level reached the highest point at 12 h post-infection." (PMID 41208976, 2025). "Similar to our analysis of NEAT1, we measured the total, nuclear, and cytoplasmic levels of ZBTB11-AS1 on days 4 and 21 post-infection (p.i.)using RT-qPCR." (PMID 40429887, 2025). "Persistent alteration in miRNAs such as miR-21, miR-146a and lncRNAs (NEAT1, MALAT1) modulates the JAK/STAT and TLR signaling pathways, influencing inflammatory gene expression and immune cell function post-infection." (PMID 40969755, 2025). "The significantly downregulated genes (NEAT1, TPM3, ZNHBA, CKLF, and OSBPL8) and the upregulated genes (ITMZC, IFNG, CD69, DNAJB9, and LYST) in NCAM1+FCGR3A+dNK cells after infection were also analyzed." (PMID 38730500, 2024). "NEAT1-2, the longer transcript of NEAT1, is mainly located in the nucleus and has been reported to facilitate IL-8 and CCL5 production by sequestering SFPQ in paraspeckles after infection with various viruses." (PMID 35495674, 2022). "Increased expression of NEAT1, MALAT1, EGOT, PVT1, MIAT has been also observed in infection with other viruses." (PMID 34940755, 2021). "The survival of Mtb in NEAT1-knockout (both NEAT1_1 and NEAT1_2) THP-1 cells reached its peak 72 h after infection, taking 0 h after Mtb infection as the baseline data; the difference was statistically significant compared with the control." (PMID 30534569, 2018). "MALAT1, in conjunction with lncRNA NEAT1, has demonstrated potential as biomarkersfor HIV infection, following the identification of elevated amounts of these long non-coding RNAs in peripheral blood mononuclear cells(PBMCs) after infection." (PMID 41393400, 2025). "Here, we observed that robust expression of NEAT1, an important lncRNA, was induced by infections with influenza A virus (IAV) and several other viruses, but the virus-induced NEAT1 expression was significantly suppressed by inactivation of STAT3 both in vitro and in vivo." (PMID 41208976, 2025).
infection (continued). "Furthermore, following infection with HIV or hantavirus, lncRNA NEAT1 interaction with other proteins and transcription factors has been found to repress the IFN-associated genes, facilitating infections." (PMID 36367091, 2022). "NEAT1 is localized to the site of infection and inflammation since it is not differentially expressed in PBMCs." (PMID 33821282, 2021). "MALAT1, along with lncRNA NEAT1, have been shown to be potential biomarkers for HIV infection, after the detection of high levels of both lncRNAs in peripheral blood mononuclear cells (PBMCs) upon infection." (PMID 32646047, 2020). "Supporting links of post-infection inflammatory and cognitive damages with cholinergic mal-functioning, man and woman-originated cultured cholinergic neurons presented differentiation-related increases of DANCR and NEAT1 targeting microRNAs." (PMID 33163005, 2020). "Upon infection, e.g., with HIV-1 or hantavirus, a (−)ssRNA emerging hemorrhagic fever related virus, this repressor complex is relocated to the paraspeckles through NEAT1 interaction, alleviating repression of ISGs, that then counteract the viral infection." (PMID 30646609, 2019). "We observed that the levels of the nuclear, polyadenylated forms of MALAT1 or NEAT1 RNA did not increase dramatically but rather declined in abundance during lytic infection, after normalization to 18S rRNA levels." (PMID 22022268, 2011). "In addition, we validated several additional genes (SLC22A8, RASSF9, and NEAT1) which were highly upregulated in Huh7.5.1 cells, yet not within this infection responsive cluster, as controls." (PMID 30700707, 2019). "RNA FISH using probes against NEAT1 was performed in HSV-1 and HCMV infected HFF cells, surprisingly no enlarged v-mPS were formed during either infection." (PMID 39592606, 2024). "A possible explanation for this observation could be that NEAT1 was up-regulated upon co-expression of ICP22 and ICP27 and in null-mutant infections of either protein, but not upon expression of either ICP22 or ICP27 alone." (PMID 36279270, 2022). "Notably, NEAT1 was upregulated upon ectopic co-expression of ICP22 and ICP27 (2.2-fold, p<10−11) and in ΔICP22 (2.1-fold, p<10−4) and ΔICP27 (4.9-fold, p<10−12) infection, but not upon expression of either ICP22 or ICP27 alone." (PMID 36279270, 2022).
neurodegenerative disease (32 papers, 2017 to 2026). A disorder of the central nervous system characterized by gradual and progressive loss of neural tissue and neurologic function. "Although NEAT1 has not been identified as risk gene for ALS by GWAS, multiple functional studies on NEAT1 suggested its essential role in neurodegenerative diseases including ALS." (PMID 37872557, 2023). "Furthermore, they linked the connection between NEAT1 and neurodegenerative diseases, which are often affected by stress." (PMID 40362651, 2025). "A protective role for the longer isoform of NEAT1 has been proposed in other neurodegenerative diseases as well." (PMID 40234480, 2025). "Some well-documented examples of lncRNAs in the context of neurodegenerative diseases are nuclear paraspeckle assembly transcript 1 (NEAT1), Homeobox transcript antisense RNA (HOTAIR), and MALAT1." (PMID 39789319, 2025). "They showed that TAR DNA-binding protein 43 (TDP-43), which is involved in neurodegenerative diseases, promotes the expression of NEAT1 by modulating the TIRR/53BP1 complex." (PMID 40362651, 2025). "Future studies should aim to elucidate the precise mechanisms by which NEAT1 affects ferroptosis and neurodegenerative diseases, and explore targeted therapies that modulate this lncRNA." (PMID 39280701, 2024). "Among the abundant lncRNAs that were upregulated by exposing the cells to Sin1 were those implicated in redox homeostasis, energy metabolism, and neurodegenerative diseases (e.g., MALAT1, MIAT, GABPB1-AS1, NEAT1, MIAT, GABPB1-AS1, and HAND2-AS1)." (PMID 36412908, 2022). "NEAT1 levels in the CNS are altered in major neurodegenerative diseases and in certain human disease models." (PMID 35266286, 2022). "Dysregulation of NEAT1 expression is associated with neuronal damage; our knowledge of the role of NEAT1 in neurodegenerative diseases is still limited." (PMID 35266286, 2022). "Many of these regulatory lncRNAs, such as MALAT1, NEAT1, HOTAIR, etc., are associated with different neurodegenerative diseases in humans." (PMID 36675966, 2022). "Recently, the lncRNA nuclear enriched abundant transcript 1 (NEAT1) was reported to play an important role in neurodegenerative diseases." (PMID 34276336, 2021). "NEAT1 levels are reported to be dysregulated in various neurodegenerative diseases, including HD." (PMID 39028820, 2024). "Interestingly, Neat1 expression was also shown to be dysregulated in several neurodegenerative diseases accompanied by neuroinflammation." (PMID 37614230, 2023). "In addition, NEAT1 dysregulation has been examined in neurodegenerative diseases, such as Huntington’s disease and multiple sclerosis." (PMID 31006037, 2019). "Relevantly, NEAT1 levels were found to be deregulated in different neurodegenerative diseases." (PMID 29997370, 2018). "Two lncRNAs (NEAT1 and TUG1) were found to be associated with neurodegenerative disease." (PMID 29653596, 2018). "NEAT1 is also hypothesized to contribute to neurodegenerative diseases." (PMID 35127819, 2021). "Moreover, several lines of evidence suggest that NEAT1 and paraspeckles may have a neuroprotective role in neurodegenerative diseases." (PMID 29997370, 2018). "The role of NEAT1 in the regulation of TDP-43 and the roles of this particular interaction in neurodegenerative diseases have been recently and specifically reviewed." (PMID 37762112, 2023). "Mounting evidence suggests a role for autophagy as part of the NEAT1 signaling pathway in various non-ischemic neurodegenerative disease models." (PMID 38212456, 2024). "Hence, these considerations prompt further investigation on the NEAT1 and PSs roles in DDR also in neurodegenerative diseases." (PMID 32630183, 2020).
neurodegenerative disease (continued). "However, no studies have explored the functions of NEAT1 in the progression of these neurodegenerative diseases." (PMID 31006037, 2019). "The NEAT1-transfected cells showed increased viability under oxidative stress, confirming that NEAT1 upregulation contributes to neuroprotective mechanisms against neuronal damage, rather than to the pathology of neurodegenerative diseases." (PMID 29499939, 2018). "The NEAT1 transfected cells showed enhanced viability under oxidative stress, confirming that upregulation of NEAT1 contributes to neuroprotective mechanisms against neuronal damage rather than pathology of neurodegenerative diseases." (PMID 30323747, 2018).
neurological disorders (8 papers, 2018 to 2025). "Furthermore, loss of Neat1 affects alternative splicing of genes important for the CNS function and implicated in neurological diseases." (PMID 32467583, 2020). "Overall, we showed that loss of Neat1 perturbs alternative splicing in the brain, with the most significant effect on the genes related to synaptic function and RNA metabolism and implicated in neurological diseases." (PMID 32467583, 2020). "Therefore, abnormal NEAT1 expression and/or regulation might underlie at least some of the symptoms and phenotypes in common neurological diseases." (PMID 32467583, 2020). "The nuclear paraspeckle assembly transcript 1 (NEAT1), a long non-coding RNA with over 200 nucleotides, exerts an indispensable impact on regulating both LD agglomeration and autophagy in multiple neurological disorders." (PMID 38212456, 2024). "In the OGD/R 1.5 hr methylation ceRNA network, Neat1, which plays critical regulatory roles in diverse neurological diseases, was shown to sponge many miRNAs and affect other lncRNA/circRNA–miRNA axes." (PMID 36880874, 2023). "The inflammatory response was also identified when limited to 389 genes upregulated through Neat1, whereas the most relevant diseases and disorders for 164 genes downregulated through Neat1 was the neurological disease." (PMID 37614230, 2023). "LncRNA NEAT1: the long noncoding RNA NEAT1, a critical regulator of paraspeckle formation in mammalian nuclei, plays a multifaceted role in glial-mediated neuroinflammation and neurological disorders through its functional dysregulation." (PMID 40791576, 2025).
cardiovascular diseases (7 papers, 2019 to 2025). "Previous studies, including our recent work, have shown that Neat1 can directly interact with Ezh2 to regulate cardiovascular diseases." (PMID 38646788, 2024). "What’s more, A to I Alu RNA editing regulated the stability of lncRNA NEAT1 in cardiovascular disease." (PMID 36358616, 2022). "Given that LncRNAs are potential therapeutic targets for cardiovascular diseases in physical exercise, we wondered whether exercise targets NEAT1 expression." (PMID 41268533, 2025). "Given that aerobic exercise has been shown to prevent AS and cardiovascular disease by targeting lncRNAs, we investigated whether exercise could regulate NEAT1 expression and macrophage ferroptosis in AS." (PMID 41268533, 2025). "Recent research has suggested that NEAT1 may also influence cardiovascular diseases." (PMID 38646788, 2024).
prostate (7 papers, 2014 to 2023). "The common lncRNA that was found to be dysregulated in both groups was nuclear-enriched abundant transcript 1 (NEAT1), and therefore, we conducted an individual analysis in order to validate this type of lncRNA as a biomarker for prostate malignancy." (PMID 33917553, 2021). "The ERα-NEAT1 axis is functional both in AR-positive and -negative cell lines, and drives prostate carcinogenesis." (PMID 25415230, 2014).
adenocarcinoma (6 papers, 2014 to 2025). A common cancer characterized by the presence of malignant glandular cells. "Processing from longer precursors is not unusual in lncRNAs, since it is already observed in the case of MALAT1 (Metastasis-associated lung adenocarcinoma transcript 1) and NEAT1 (Nuclear enriched abundant transcript 1)." (PMID 34461828, 2021). "Other p63-regulated lncRNAs include NEAT1 (Nuclear paraspeckle assembly transcript 1) and MALAT1 (Metastasis-associated lung adenocarcinoma transcript 1), whose expression suppresses epidermal differentiation." (PMID 41296428, 2025).
immune diseases (6 papers, 2017 to 2025). "In addition, NEAT1 directly acts on the expression of inflammatory factors to participate in immune disorders, and accelerates the inflammatory response." (PMID 33710444, 2021). "The upregulation of NEAT1 has been shown to promote the release of several inflammasomes (NLRP3, NLRC4, and AIM2) and pro-inflammatory cytokines (CXCL10, IL-6, and IL-1β), resulting in an immune response in inflammatory and immune diseases." (PMID 35127819, 2021).
digestive system tumors (4 papers, 2017 to 2024). "Specifically, firstly, the search was not comprehensive, articles after 2020 were not included, and new original studies on the relationship between NEAT1 and prognosis of patients with digestive tumours have emerged in recent years." (PMID 39139172, 2024). "Previous studies have analysed the relationship between NEAT1 and the prognosis of patients with gastrointestinal tumours, however, there are many limitations in this study." (PMID 39139172, 2024). "High NEAT1 expression correlated with poor prognosis of digestive system tumor (HR=1.54, 95% CI: 1.37–1.73) and Respiratory carcinomas (HR=1.44, 95% CI: 1.11–1.85) patients." (PMID 28507281, 2017). "In addition, our overall finding suggested an elevated expression of NEAT1 was related to a poor prognosis in patients with digestive system neoplasms." (PMID 28118609, 2017). "So far, there is no research on the mechanism of action of NEAT1 in digestive system tumors." (PMID 28118609, 2017).